BAP1 (BRCA1 associated deubiquitinase 1)
Diseases named in the same sentence as BAP1 in open-access papers (continued):
Sharing a sentence is not in itself a finding about the gene and the disease.
tumor (846 papers, 2008 to 2026). "Lastly, in tuberous sclerosis, hypopigmented macules and tumors occur with tuberin loss and mTOR activation, phenotypes reversed with topical rapamycin, thereby raising the possibility for rapamycin in BAP1-associated neoplasia." (PMID 41480773, 2026). "Among the three genes, the loss of SETD2 is typically a subclonal event, whereas the loss of PBRM1 or BAP1 usually occurs as a clonal event earlier in tumor progression." (PMID 41602827, 2026). "Among these, BAP1 loss has emerged as one of the most consistently validated indicators of aggressive tumor behavior." (PMID 42122167, 2026). "This resistance would enable BAP1-deficient cells to evade cell death and consequently promote tumor growth." (PMID 41602827, 2026). "BIMT show a bi‐allelic inactivation of the BAP1 tumour suppressor gene located on chromosome 3q21, which can be caused by loss‐of‐function mutations or by deletion affecting the BAP1 locus." (PMID 39268598, 2025). "The BAP1 gene, located on chromosome 3, encodes BRCA1-associated protein 1 and functions as a tumor suppressor." (PMID 41154665, 2025). "BAP1 mutations lead to the loss of tumour suppressor functions, impacting chromatin remodelling, DNA repair, and cell cycle regulation, thereby promoting tumour progression." (PMID 40794619, 2025). "BRCA1-associated protein 1 (BAP1) functions as a tumor suppressor that regulates cell cycle progression, differentiation, cell death, and DNA damage response." (PMID 41226789, 2025). "As a critical tumor suppressor gene, mutational inactivation of BAP1 can lead to “BAP1 cancer syndrome” and the development of various sporadic tumors." (PMID 40918144, 2025). "Treatment with SRC inhibitors and autophagy inducers exhibited synergism invitro, in ovo and in patient-derived tumor organoids with BAP1 loss, paving the way for treating BAP1-deficient cancers with autophagy inducers and kinase inhibitors." (PMID 40754831, 2025). "BAP1 loss correlates with more clinically aggressive sporadic ccRCC given its association with high tumor grade and worse survival outcomes for patients." (PMID 40510153, 2025). "These include tumour-suppressor BAP1 expression loss (often accompanied by monosomy 3), chromosome 8 gain, and epithelioid cell type." (PMID 40361330, 2025). "Prognostically-relevant molecular tumour subtypes can be distinguished based on the presence of additional drivers: a so-called ‘BSE mutation’ in BAP1, SF3B1 or EIF1AX and copy number alterations (CNAs) affecting chromosome 3p or 8q." (PMID 40240901, 2025). "Preclinical studies have shown that EZH2 inhibition suppresses tumor growth, particularly in PM harboring BAP1 loss." (PMID 41463268, 2025). "It is known that breast cancer type 1 susceptibility protein-associated protein-1 (BAP1) is a broad-spectrum tumor suppressor in many cancer types." (PMID 40723336, 2025). "BAP1 demonstrates a tumour suppressor function, evident both in the tumour predisposition syndrome and in global and tissue‐specific knockouts in mouse models." (PMID 39976080, 2025). "Our case had polybromo-1 (PBRM1) and BAP1 functional loss, tumor mutational burden of 4 Muts/Mb, stable microsatellite status, and a PD-L1 tumor proportion score of <1%." (PMID 41199851, 2025). "The objective response rate (ORR) was 9% and 27% of patients had a reduction in tumor size, including those with BAP1-mutated disease." (PMID 41440218, 2025). "BAP1‐inactivated tumours (BIMT) are indolent proliferations of dermal epithelioid melanocytes with nuclear loss of BAP1, and can present with severe cytological atypia." (PMID 39268598, 2025). "BIMT are indolent tumours characterised by large dermal epithelioid melanocytes with nuclear loss of BAP1, and present with a variable amount of cytological atypia and low mitotic activity." (PMID 39268598, 2025).
tumor (continued). "Tumors with BAP1 mutations exhibited a significantly more optimized therapeutic ratio—which was adjusted for the relative difference in the tumor growth rate of each cell line—than tumors with other mutations." (PMID 40856833, 2025). "BRCA1-associated protein 1 (BAP1) is a tumor-suppressor gene located on human chromosome 3p21.3 and encodes a ubiquitin carboxy-terminal hydrolase." (PMID 41561288, 2025). "Our study demonstrated that the BAP1 mutation is associated with rapid tumor progression and the therapeutic responses to JX-594 were most pronounced in cells with BAP1 mutations." (PMID 40856833, 2025). "BAP1 is linked to an inflamed tumor microenvironment and the infiltration of cytotoxic T cells, suggesting a possible synergistic activity of the combination of immunotherapy and PARP inhibitors." (PMID 40361508, 2025). "By integrating radiologic features with genomic markers such as BAP1 mutations, monosomy 3, and chromosome 8q gain, AI models can predict tumor radiosensitivity and guide dose modulation based on individual tumor biology." (PMID 40901108, 2025). "At the molecular level, BRCA1-associated protein-1 (BAP1) emerges as a key tumor suppressor frequently inactivated in both germline and somatic settings." (PMID 41375066, 2025). "BRCA-associated protein 1 (BAP1) is a tumor suppressor gene inactivated in approximately 60% of MPMs." (PMID 39941848, 2025). "While Case 1, Case 2, and Case 3 all had somatic BAP1 mutations in the tumor, the time it took to develop distant metastasis was very different." (PMID 40283643, 2025). "The BAP1 gene was identified in 1998 as a powerful tumor suppressor gene, and, in 2011, its association with germline and somatic carcinogenesis of PM was defined." (PMID 40361508, 2025). "Definitive diagnosis of WDPMT was established through comprehensive immunohistochemistry (retained BAP1 expression) and next-generation sequencing, which revealed a low tumor mutational burden and a pathogenic GPR124 mutation." (PMID 41327683, 2025). "Loss-of-function mutations in BAP1, a tumor suppressor involved in chromatin remodeling, are associated with poor prognosis." (PMID 40869967, 2025). "We have previously shown that two genes that are frequently mutated in ccRCC, PBRM1 (50%) and BAP1 (15%), are associated with tumor grade and aggressiveness." (PMID 40097393, 2025). "Loss of the nuclear localization of BAP1 protein contributed to enhanced cell migration and promoted more aggressive tumor behavior in human HCCs." (PMID 39984455, 2025). "Other gene mutations are also involved in the formation of RCC: PBRM1 is potentially associated with tumor immune escape; BAP1 and SETD2 participate in DNA repair regulation; and MTOR regulates the critical PI3K/AKT/mTOR signaling pathway." (PMID 41405787, 2025). "Immunohistochemical analysis indicates a loss of nuclear BAP1 expression in tumor cells, with positive staining in internal control cells like inflammatory and stromal cells." (PMID 40506895, 2025). "Recent studies have investigated the relationship between BAP1 deficiency and the tumor immune microenvironment in PM." (PMID 40361508, 2025). "Our cohort showed that weak BAP1 nuclear expression is associated with poorer prognosis, higher Gleason scores, and advanced tumor stages." (PMID 40136571, 2025). "For subgroup analysis by genetic mutations, the CDX model with BAP1 mutations exhibited the most rapid tumor growth rate, compared with the models with VHL, PBRM1, and SETD2 mutations (P < 0.01)." (PMID 40856833, 2025). "The efficacy of SRC inhibitors and autophagy inducers in treating cancers with loss of BAP1 was further validated through the use of patient-derived tumor organoids (PDTOs) as preclinical models." (PMID 40754831, 2025). "Pathogenic variants in the BAP1 gene increase the risk of tumor predisposition to uveal and cutaneous melanoma, malignant mesothelioma, and renal cell carcinoma." (PMID 40649916, 2025).
tumor (continued). "Low expression of BAP1 is positively correlated with aggressive tumor phenotypes, and is independently associated with poorer recurrence-free survival and overall survival following curative hepatectomy." (PMID 40607251, 2025). "To summarize, this study uncovered the underlying mechanisms of the regulation of BAP1 and that loss of the nuclear localization of BAP1 protein contributed to enhanced cell migration in vitro and more aggressive tumor behavior in human HCCs." (PMID 39984455, 2025). "This typical resistance pattern is often associated at the molecular level with mutations in genes such as BAP1, an immunosuppressive microenvironment, or low tumor mutational burden." (PMID 41395612, 2025). "BRCA1-associated protein 1 (BAP1) is a tumor suppressor gene in which germline inactivating mutations lead to atypical intradermal melanocytic tumors and a small proportion of sporadic cutaneous melanoma." (PMID 38927967, 2024). "At the same time, mutations in PBRM1 and BAP1, the drivers of tumor evolution, also showed significant differences in our subtypes." (PMID 39513109, 2024). "BAP1 is an important tumor suppressor, and inactivating mutations of BAP1 have been identified in a variety of malignancies." (PMID 39587076, 2024). "BAP1-altered MPM are associated with a more inflammatory tumor microenvironment and seem to constitute a distinct immunogenic class, with possible implications for immunotherapeutic response." (PMID 39091916, 2024). "An additional tumor suppressor involved in ferroptosis regulation is BRCA1-associated protein 1 (BAP1), which is mutated in many cancer types." (PMID 38539554, 2024). "Haploinsufficiency of the BAP1 gene in MPM has also been associated with strong immunogenicity of the tumor microenvironment and hyperactivation of immune checkpoint receptors PD-1, PD-L1 and CTLA4." (PMID 39091916, 2024). "BAP1 loss of expression was found in one third of all RM at diagnosis and increased to 100% in subsequent tumor recurrences." (PMID 38785832, 2024). "The potential of radiomics for identifying BAP1 mutations from the CT scans of PM patients was demonstrated; 2D features extracted from tumor segmentations yielded an AUC value of 0.69 [0.60, 0.77] when using a decision tree classifier." (PMID 39669009, 2024). "The tumor suppressor function of BAP1 is linked to its dual activity in the nucleus, (where it is involved in DNA repair and transcription), and in the cytoplasm (where it regulates cell death and mitochondrial metabolism)." (PMID 38785832, 2024). "Aberrant expression of the BAP1 tumor suppressor gene is a prominent risk factor for several tumor types and is important in tumor evolution and progression." (PMID 38045292, 2024). "Identification of missense variants with effects more minor than those of null variants is likely to provide further insights into BAP1-TPDS tumor profile and prevalence." (PMID 37956408, 2024). "As a well-established tumor suppressor, BAP1 is mutated across a variety of human cancers, and patients with BAP1 mutations often exhibit worse prognosis." (PMID 39587076, 2024). "Recent studies have shown that variants in the BAP1 gene cause a tumour susceptibility syndrome, which is characterised by an increased incidence of early tumours." (PMID 39336594, 2024). "Mutations in PBRM1 and SETD2 often co-exist while mutations in PBRM1 and BAP1 seem mutually exclusive at the clone level, with distinct tumor phenotypes." (PMID 37999735, 2024).
tumor (continued). "Studies investigating the mechanism have shown that BAP1’s tumor suppressor role is associated with its dual function." (PMID 39201746, 2024). "BAP1 has emerged as a critical tumor suppressor in various cancer types, increasing susceptibility to tumor formation when mutated either in the germline or somatically." (PMID 39201746, 2024). "BRCA1-associated protein 1 (BAP1) acts as a tumor suppressor and can affect the cell cycle, tumor immunity, and cellular metabolism through multiple pathways." (PMID 39587076, 2024). "Recently we showed in a validation study of two cohorts that the BRCA1-associated protein 1 (BAP1) expression in tumor was a strong and independent predictor of survival in PM patients treated with first-line pemetrexed-platinum." (PMID 38280040, 2024). "We observed epigenetic upregulation of EMT-related genes, particularly in tumours harbouring BAP1 somatic cancer driver mutations, which are linked to advanced-stage tumours, distant metastasis, and poorer prognosis." (PMID 39592856, 2024). "Recent studies have shown that BAP1 mutations are associated with an inflammatory tumor microenvironment and increased immune cell infiltration, suggesting a potential role as a predictive biomarker for immunotherapy response." (PMID 38903495, 2024). "The other frequently mutated tumor suppressor, BAP1, which encodes a deubiquitinating enzyme, reduces histone H2A ubiquitination on the SLC7A11 promoter region to repress SLC7A11 expression and consequently promotes ferroptosis." (PMID 38908072, 2024). "BAP1 loss, in particular, has been associated with a high tumor grade and worse survival outcomes for patients with clear cell RCC." (PMID 38791999, 2024). "The biallelic loss of BAP1 was confirmed in four of the seven tumours by a combination of monosomy 3 or loss of chromosome 3p and sequence variants; whereas, in three tumours, only monosomy 3 or loss of chromosome 3p was detected." (PMID 39766052, 2024). "For example, research identified BRCA1-associated protein 1 (BAP1) as a tumor suppressor that is possibly related to the development of salivary duct and intracapsular carcinoma." (PMID 38392182, 2024). "BRCA1-associated protein 1 (BAP1) is a nuclear-localised UCH-family DUB originally reported as a tumour suppressor, with its DUB activity linked to promoting HR-mediated repair of DSBs." (PMID 38572758, 2024). "For instance, the loss of BAP1 has been related to an immunosuppressive tumor microenvironment via the PROS1/MERTK ligand, which activates immunosuppressive CD163+ macrophages." (PMID 38920653, 2024). "The DFI reflects the genetic alterations in the primary tumor, such as monosomy 3 and BAP1 mutation, which lead to the earlier onset of metastases via a shorter liver intrahepatic metastatic dormancy." (PMID 39410027, 2024). "BAP1 functions as a tumor suppressor and is associated with poor prognostic factors (class 2 genetic profile) and higher metastatic risk." (PMID 38732371, 2024). "Given its protective role, BAP1 loss is established as “a foe” when it comes to tumour susceptibility and development." (PMID 38459714, 2024). "BRCA1-associated protein 1 (BAP1) is a nuclear deubiquitylase and functions as a tumor suppressor in MPM." (PMID 38610930, 2024). "This study further explains the specific mechanism by which a mutation in BAP1 can lead to both increased glycolysis levels and lactate production in tumor cells." (PMID 39587076, 2024). "To this end, we report on the role of deubiquitinase BRCA1‐associated protein‐1 (BAP1), a tumour suppressor gene with a widely acknowledged role in the corrupted signalling and metabolism of PMe." (PMID 38459714, 2024).
tumor (continued). "Recently, it has been shown that multiple subclonal drivers including PBRM1, SETD2, or BAP1 mutations contribute to high genetic intra-tumor diversity in ccRCC and impact on clinical outcomes." (PMID 37999735, 2024). "A cohort of 149 patients with PM and known somatic BAP1 mutation status was collected, and a previously published deep learning model was used to first automatically segment the tumor, followed by radiologist modifications." (PMID 39669009, 2024). "BAP1 (BRCA1 associated protein-1) a ubiquitin carboxy-terminal hydrolase is a tumor suppressor and prevents metastatic spread." (PMID 38758815, 2024). "BRCA 1-Associated Protein-1 (BAP-1) is a pivotal anti-tumor protein that binds to the Breast Cancer 1 (BRCA-1) gene and plays a crucial role in deubiquitinating ubiquitin." (PMID 39796121, 2024). "Studies identified BAP1 as a tumor suppressor in ccRCC and was associated with aggressiveness, high‐grade nuclear features, metastasis." (PMID 38923304, 2024). "Therapeutic strategies based on the biological function of BAP1 have been developed and evaluated for tumor patients harboring BAP1 deficiencies or alterations, such as histone deacetylase (HDAC) inhibitor, EZH2 inhibitor and PARP inhibitor." (PMID 39350280, 2024). "The tumor from one germline BAP1 carrier (stage IIIC) with a somatic EIF1AX splice variant, has not developed metastasis within a 22-year observation time." (PMID 39378214, 2024). "Aberrant expression of the BAP1 (BRCA associated protein 1) tumor suppressor gene is a prominent risk factor for several tumor types and is important in tumor evolution and progression." (PMID 39554490, 2024). "Another potential link between PD and cancer is ubiquitin C-terminal hydrolase BRCA1-associated protein 1 (BAP1), a tumor suppressor and a known genetic risk factor for PD." (PMID 38612708, 2024). "In 64.5% of patients in the present study, loss of nuclear staining was detected in tumor tissue, indicating the presence of a BAP1 mutation by IHC staining." (PMID 38280040, 2024). "It turned out that genetic variants of BAP1 can cause high risk not only to UM but also to a spectrum of other neoplasia." (PMID 35920959, 2023). "BRCA1-associated protein 1 (BAP1) deficiency, primarily caused by its expression losses and mutations, triggers molecular mechanisms that drive tumour growth and impact UM outcome, making it a powerful prognostic biomarker." (PMID 37454231, 2023). "We found that ccRCCs harboring a PTEN or BAP1 mutation showed the lowest level of Granzyme B positive tumor-infiltrating lymphocytes (TILs)." (PMID 36562826, 2023). "It was decided that the management and treatment of specific tumours associated with BAP1 GPV and assessment of BAP1 variants of uncertain significance was outside the scope of this guideline." (PMID 37607989, 2023). "BRCA-associated protein 1 (BAP1) loss (known for 204 cases) was associated with increased tumor pigmentation (P = 0.001)." (PMID 37193315, 2023). "We performed BAP1 mutation analysis targeting the oncogenic variants detected in the tumor on DNA from matched peripheral blood (50 patients)." (PMID 35920959, 2023). "Loss of BAP-1 expression correlates strongly to gene expression class, monosomy 3, tumor size, and ciliary body involvement." (PMID 37052618, 2023). "In turn, M3 is associated with virtually all other strong predictors: larger tumour size, BAP1 mutation, gene expression class 2, vasculogenic mimicry patterns, extraocular extension and tumour cell morphology." (PMID 35801361, 2023). "We found six heterozygous variants predicted to alter splicing; two in DNA repair-associated genes (BRCA1 and BAP1) and four in tumor suppressor genes (ARHGEF10L, ELL, MYH9, and NCOR2)." (PMID 37234870, 2023). "This study aims to reveal the possible molecular mechanism of BRCA1-associated protein 1 (BAP1) mutations in affecting the tumor immune microenvironment in UM through mediating the nuclear factor-κB (NF-κB) signaling pathway." (PMID 37710185, 2023).